Y_RNA (Y RNA )
Gene: Miscellaneous RNA gene on chromosome 21 (5,597,390 to 5,597,490, forward strand). Ensembl gene ENSG00000277777.
Homologues: Orthologues: chimpanzee Y_RNA (100% identical). Paralogues in human: Y_RNA (100% identical), Y_RNA (86% identical), RNY3 (85% identical), Y_RNA (85% identical), RNY3P1 (84% identical), Y_RNA (84% identical), RNY3P11 (83% identical), Y_RNA (83% identical), Y_RNA (82% identical), Y_RNA (81% identical), RNY3P3 (80% identical), Y_RNA (80% identical), and 95 more.